INS (insulin)
Diseases named in the same sentence as INS in open-access papers (continued):
Sharing a sentence is not in itself a finding about the gene and the disease.
Insulin resistance (continued). "Arsenic has also been correlated with the onset of insulin resistance downregulating insulin gene expression and interfering with insulin granule exocytosis through calpain-10-mediated proteolysis and activation of SNAP-25." (PMID 32481506, 2020). "Diabetes results from reduced insulin secretion from pancreatic β-cells, insulin resistance in peripheral tissue, or both." (PMID 32727064, 2020). "In human trials, 100 g/day for 15 days of flavonoid-rich chocolate in patients with essential hypertension led to a reduction of insulin resistance with an improvement of insulin sensitivity and beta-cell function." (PMID 33218062, 2020). "Women with PCOS have more reduced metabolic flexibility (evaluated through changes in the respiratory quotient after insulin stimulation) when have hyperandrogenism, high BMI and Insulin resistance." (PMID 32103756, 2020). "The development of insulin resistance is accompanied with a parallel increase in insulin secretion in order to maintain euglycemia." (PMID 32752280, 2020). "The overproduction of the RAS, including Ang II, activation of the AT1R, and increased production of aldosterone, impairs insulin signaling, further exacerbating insulin resistance." (PMID 32235782, 2020). "Here we examined how HGSD treatment attenuated GR-mediated alteration in PI3K signalling and insulin resistance in diabetic rats, dexamethasone-treated mice and in insulin resistant C2C12 skeletal muscle cells." (PMID 32792855, 2020). "Insulin resistance was assessed by the homeostasis model assessment of insulin resistance (HOMA-IR) as follows: HOMA-IR: [glucose (mmol/l) × insulin (mU/l)]/405." (PMID 32160900, 2020). "Of note, there are similarities and discrepancies in gene expression changes between our insulin resistance protocol and the published chronic insulin treatments." (PMID 32718202, 2020). "Donkeys have a decreased insulin sensitivity compared to horses and donkeys with insulin resistance often have higher insulin plasma concentrations than horses with insulin dysregulation." (PMID 33302557, 2020). "The disruption of a proper insulin stimulation that affects glucose transport to skeletal muscle cells and adipocytes via GLUT type 4 is the cause of peripheral insulin resistance that often occurs in PCOS." (PMID 32992734, 2020). "The HOMA-IR index indicates insulin resistance based on the amount of fasting plasma glucose and insulin." (PMID 32635185, 2020). "Insulin resistance is defined as the inability of insulin-sensitive tissues, such as skeletal muscle, liver, adipose, and brain, to respond appropriately to insulin." (PMID 32183037, 2020). "A previous study revealed that a DENND1A SNP in the dominant model resulted in significantly higher insulin levels after 75-g OGTT and an increased risk of insulin resistance in type 2 diabetes patients." (PMID 32591571, 2020). "The insulin levels of CP-treated db/db mice were significantly decreased and the surrogate biomarker for insulin resistance, especially HOMA-IR level, was lower than the chrysin group." (PMID 33255372, 2020). "Low dose streptozotocin is known to induce rapid destruction of pancreatic β-cells leading to impaired glucose stimulated insulin release and insulin resistance, both of which are marked features of type 2 diabetes." (PMID 32013797, 2020). "Prediabetes and type 2 diabetes are characterized by defects in insulin secretion and insulin resistance, which leads to a decrease in whole-body glucose disposal." (PMID 32411098, 2020). "Obesity is a major threat for patients with T1DM as it triggers a vicious cycle where weight gain leads to insulin resistance which, in turn, leads to increased insulin requirements to achieve glycemic control, resulting in further weight gain." (PMID 33071965, 2020). "Insulin treatment decreases insulin resistance, and the production of the residual beta-cells starts becoming sufficient again, even though the destruction process continues." (PMID 32635304, 2020).
Insulin resistance (continued). "Recent reviews cover the regulation of insulin signaling and development of insulin resistance in podocytes in more detail." (PMID 33321755, 2020). "Elevated Se intake and selenoprotein expression levels have been associated with impaired hydrogen peroxide-dependent signaling by insulin, leading to hyperglycemia and insulin resistance." (PMID 32905881, 2020). "Insulin resistance leads to increased production of insulin to compensate for its impaired signaling, which is accompanied by increased production of IAPP." (PMID 32604774, 2020). "Insulin resistance is generally defined as an insufficient response to insulin by target cells and represents a central feature of metabolic disorders, including T2DM and obesity." (PMID 32733190, 2020). "Chronically elevated levels of IL-6 have been shown to decrease hepatic insulin sensitivity in vitro, to induce hyperinsulinemia in mice and to mediate insulin resistance in murine muscle tissue." (PMID 33178196, 2020). "FXR activation was found to increase the release of anti-inflammatory cytokines and insulin-sensitive adipokines (adiponectin and leptin), and then reversed insulin resistance." (PMID 32982723, 2020). "In high fat diet-induced obesity and insulin resistance, the supplementation with Myrciaria jaboticaba berry increased insulin sensitivity, thus prevented tau phosphorylation and improved learning/memory performance." (PMID 33267804, 2020). "Many studies have shown that increased plasma FFA levels can trigger insulin resistance and inflammation in the major insulin target tissues, thus linking obesity with insulin resistance and the development of T2D25." (PMID 32532984, 2020). "Resistin is a pro-inflammatory adipokine that positively correlates with hyperglycemia and insulin resistance in obesity, and both peripheral and hypothalamic administrations of resistin impair insulin signaling." (PMID 33097799, 2020). "When a normal or elevated insulin level produces an attenuated biological response, this is defined as insulin resistance." (PMID 32971810, 2020). "Angiotensin II (AngII) disturbs insulin signaling at various levels, thereby giving rise to insulin resistance." (PMID 33270683, 2020). "Combined with local and systemic inflammation, this leads to widespread insulin resistance, which in turn, results in increased insulin demand as the body attempts to maintain glucose homeostasis." (PMID 33233816, 2020). "In this study, we found that the association between genetically predicted serum IGF-1 levels and type 2 diabetes was partially attenuated after adjustment for fasting insulin levels or insulin resistance through multivariable MR analysis." (PMID 32548700, 2020). "Since insulin resistance is associated with activation of TLR4-initiated inflammation, the impact of carrageenan exposure on glucose tolerance and insulin signaling in C57BL/6J mice was tested." (PMID 32377523, 2020). "Chronic tissue inflammation leads to increased levels of pro-inflammatory cytokines, such as TNF-α and IL- lβ, which impair insulin signaling and induce insulin resistance." (PMID 33028294, 2020). "AA can help alleviate symptoms arising from fatty liver and insulin resistance by inhibiting lipid accumulation in cells, as well as lowering liver fat content and enhancing insulin activity in mice." (PMID 32148789, 2020). "Participants with T2DM were confirmed to be more insulin resistant than the controls (homeostatic model assessment of insulin resistance, 1.3±0.8 versus 4.3±2.5; P=0.005), with higher fasting blood sugar." (PMID 32078413, 2020). "This is based on our observation that TRT reduced HbA1c by 0.67%, fasting blood glucose by 0.86 mmol/L, and fasting insulin and insulin resistance index (HOMA-IR) by 1.23." (PMID 33061966, 2020). "HOMA-IR mainly reflects insulin sensitivity in fasting state, that is, the degree to which insulin inhibits liver sugar output, and also the severity of liver insulin resistance." (PMID 32528557, 2020).
Insulin resistance (continued). "It has been reported that fasting insulin (an indicator of insulin resistance) contributed to the development of the metabolic syndrome, including hypertension, hypertriglyceridemia, reduced HDL-C, and T2D." (PMID 32982723, 2020). "Nebivolol improves insulin resistance-related variables (fasting glucose, fasting insulin, and HOMA-IR; P < 0.001, 0.01, and 0.01 respectively)." (PMID 32990863, 2020). "Insulin plays a key role in regulating cellular metabolism, and insulin resistance leads to several metabolic changes that can induce the development of cardiovascular disease, such as imbalances in glucose and lipid metabolism." (PMID 32703284, 2020). "The alterations in the post receptor insulin signaling cascades result in the development of insulin resistance." (PMID 33198177, 2020). "During insulin resistance in type 2 diabetes, the inhibitory effect of insulin on hepatic gluconeogenesis is reduced, and the expressions of gluconeogenesis proteins PEPCK and G-6-Pase were increased." (PMID 32280711, 2020). "A recent study did, in fact, determine that growing IB pigs can develop insulin resistance at an early stage and that insulin is less effective in IB than in Landrace pigs." (PMID 32326415, 2020). "An increase in FFA level in insulin resistance is partially responsible for the typical high basal insulin response to glucose." (PMID 32796572, 2020). "First, the TyG index had better predictive ability for the incidence of prediabetes than the obesity indices of BMI and WC, lipid profiles of TG and HDL-C, and non-insulin-based insulin resistance indices of TG/HDL-C and Mets-IR." (PMID 33059672, 2020). "Consistently, we found postprandial insulin level was lower and insulin resistance was higher in patients with the highest tertile of CV than those with the lowest tertile." (PMID 32887588, 2020). "We believe that the Kuma mutant will serve as an attractive model not only for the studies of the Insulin gene and the molecular mechanism for the maintenance of beta-cell mass, and the development of insulin resistance under hyperglycemia." (PMID 32699230, 2020). "Long-term insulinization has also been involved with the establishment of insulin resistance, thus requiring a progressive increase in the insulin dose to achieve the antihyperglycemic response, increasing the risk of hypoglycemia." (PMID 32566072, 2020). "Deregulated insulin secretion and progressive insulin resistance are two main characteristics of T2DM." (PMID 32582032, 2020). "The outcomes of the study provide evidence that demonstrates the antihyperglycemic effect of RH‐XOS partly due to the attenuation of insulin resistance and an improvement in muscle glucose uptake as well as insulin signaling in type 2 diabetic rat model." (PMID 31993169, 2020). "This insulin resistance results in a hyperglycemic condition, which increases the burden on pancreatic beta cells to produce more insulin and consequently, ER stress develops, leading to the development of type 2 diabetes due to beta cell loss." (PMID 32397116, 2020). "During insulin resistance, NO production is impaired while the supportive effect of insulin on calcium ion influx (via PI3K delta and possibly the MEK–ERK pathway) and vasoconstriction is still present." (PMID 32819363, 2020). "Daily doses of DPP4 inhibitors do not result in decreased plasma insulin levels or ameliorated insulin resistance in insulin-resistant, hyperinsulinemic individuals." (PMID 32211075, 2020). "GSK3 is a negative regulator of insulin signalling, strongly linked with insulin resistance and numerous studies targeting GSK3 provide compelling evidence for GSK3-inhibition improving insulin sensitivity as a therapeutic target in T2DM61–65." (PMID 31969632, 2020). "The presence of peripheral insulin resistance and increased pancreatic insulin secretion have been reported in this animal model." (PMID 32033223, 2020).
Insulin resistance (continued). "Exposure of L6 cells to HI levels (100 nM) for 24 h decreased the acute-insulin-stimulated 2DG uptake, indicating insulin resistance." (PMID 32230718, 2020). "A single dose of D-Pinitol was described to lower the plasma levels of glucose in healthy subjects, and in patients with T2DM, and long-term treatment with D-Pinitol decreased hyperglycemia and insulin levels in patients with insulin resistance." (PMID 32650579, 2020). "The steatotic hepatocyte is associated with dysregulated lipolysis resulting in excessive delivery of fatty acids to the liver, de novo lipogenesis, impaired post-receptor signaling by insulin (i.e., insulin resistance)." (PMID 33266360, 2020). "Hyperinsulinemia also increased insulin resistance in humans over 2 day treatment with exogenous insulin, and in patients with insulinomas." (PMID 32326226, 2020). "In any case, plakoglobin seems to enhance insulin potency by triggering intracellular signals, and reduced plakoglobin function is likely to contribute to the development of insulin resistance in type 2 diabetes and perhaps also in DMD7,8." (PMID 32170063, 2020). "Women with GDM exhibited higher fasting maternal blood C-peptide, insulin, glucose plasma levels and homeostatic model assessment of insulin resistance (HOMA-IR) compared to the NGT group." (PMID 31940889, 2020). "MNAM activates SIRT1 and inhibits acetylation of FOXO1, which in turn regulates insulin sensitivity in type 2 diabetic mice, leading to a reduction of hepatic glucose output and improvement of insulin resistance." (PMID 32280711, 2020). "Insulin resistance (HOMA2-IR) and beta cell function (HOMA2-%β) were both associated with intervention-induced change in insulin tAUC between SIT and EX+BR." (PMID 33308235, 2020). "Glucocorticoids induce hyperglycemia by increasing insulin resistance through post-receptor insulin signaling defects." (PMID 31876135, 2020). "Elevated oxidative stress caused by reactive oxygen species (ROS) plays a causal role in the pathogenesis of DM and related complications via increased insulin resistance or impaired insulin secretion." (PMID 32013162, 2020). "Increased plasma insulin levels (hyperinsulinemia) develop to counterbalance initial peripheral insulin resistance, but strong evidence indicate that this contributes to and exacerbates insulin resistance." (PMID 32230718, 2020). "These molecules are known to decrease insulin resistance, increase insulin sensitivity, and have diverse properties with importance from cell signaling to metabolism." (PMID 33139672, 2020). "ketogenic diets induce severe hepatic insulin resistance in mice through impairments in insulin suppression of endogenous glucose production during a hyper-insulinemic euglycemic clamp." (PMID 32670384, 2020). "In this regard, strategies to counteract insulin resistance should elicit possibility to link muscular lipid utilization and insulin signaling improvement." (PMID 33171690, 2020). "Insulin resistance, also known as low insulin sensitivity, is a common feature of many human diseases." (PMID 32092075, 2020). "Insulin resistance, a condition typically defined as an inability of insulin to appropriately clear glucose from the bloodstream, is a risk factor for diabetes, heart disease, and NASH." (PMID 32849276, 2020). "Adipose tissue insulin resistance is characterized by a deficiency in GLUT4, and rosiglitazone, a well-known insulin-sensitizer, acts at least in part by enhancing GLUT4 expression." (PMID 32138197, 2020). "CRP is a prominent biomarker for insulin resistance and CVD, and SAA antagonizes insulin action in adipocytes, thus contributing to systemic insulin resistance." (PMID 32158768, 2020). "The abundances of targeted c-miRNAs, with reported functions in metabolic regulation, were analysed in response to a high-carbohydrate meal in healthy weight insulin-sensitive (IS) and overweight insulin-resistant (IR) women." (PMID 32042348, 2020).
Insulin resistance (continued). "Insulin glycation is an example of glycation of short-lived protein that can lead to insulin resistance because of its reduced biological activity." (PMID 33053901, 2020). "The decrease of SCFAs leads to the decrease of the number of islet cells and the decrease of insulin sensitivity, which in turn leads to insulin resistance (IR)." (PMID 33181668, 2020). "The oral administration of Ga caused dose-dependent decreases in metabolic parameters including hepatic TG contents, hyperglycemia with insulin resistance, and blood levels of insulin and leptin." (PMID 32792584, 2020). "In our studies, we found that SCU can decrease the levels of serum TG, CHO, glucose, insulin and improve insulin resistance induced by HFHS diet and STZ treatment." (PMID 33362535, 2020). "Ovarian NGF overexpression leads to hyperinsulinemia and insulin resistance, but with a preserved hepatic insulin sensitivity and normal glucose production." (PMID 32310267, 2020). "In response to insulin resistance, insulin secretion increases in order to maintain normal glucose homeostasis." (PMID 32704559, 2020). "Among common flavonoids, various studies have indicated that both quercetin and kaempferol exert potential anti-diabetic activities in modulating insulin secretion and managing insulin resistance." (PMID 32722185, 2020). "Insulin resistance is a state in which normal concentrations of insulin fail to achieve an appropriate biological response downstream of the insulin receptor." (PMID 32679915, 2020). "Chronic kidney disease (CKD) is associated with insulin resistance and, in advanced CKD, decreased insulin degradation." (PMID 33187372, 2020). "A common problem with animal-source insulins, however, was the formation of anti-insulin antibodies, which led to lipoatrophy and insulin resistance in a significant percentage of patients." (PMID 32396624, 2020). "Expression of the fasting blood glucose, fasting insulin level and insulin resistance index(HOMA-IR) in rats of each group." (PMID 32903815, 2020). "As already described for the liver, elevated storage of intracellular TAGs is a marker of disordered FA metabolism, and DAGs and CERs are bioactive lipid intermediates inducing insulin resistance by interfering with insulin signaling." (PMID 32796572, 2020). "HOMA-IR and HOMA-β were used to assess insulin resistance and insulin secretion levels with different glucose statuses." (PMID 32184821, 2020). "Insulin resistance of skeletal muscle is mainly manifested in the decrease of glycogen synthesis stimulated by insulin, which in turn leads to the decrease of glucose transport." (PMID 32438641, 2020). "In the early stage of intensive insulin therapy, patients have obvious insulin resistance and islet cell dysfunction." (PMID 33015194, 2020). "Insulin resistance is defined as a pathological condition in which insulin effect is impaired in peripheral target tissues such as the skeletal muscle, liver, and adipose tissue." (PMID 32907593, 2020). "Fresh PGJ was found to increase the level of insulin and ameliorate insulin resistance in people with impaired fasting glucose." (PMID 31993180, 2020). "GLUT4 is an insulin-regulated glucose transporter, primarily expressed in the adipose tissue and striated muscle, which mediates glucose uptake, thus alleviating insulin resistance." (PMID 32657640, 2020). "For example, it has been proposed that circulating fetuin-A modulates the insulin sensitivity and insulin resistance in organs such as adipose, liver, and other tissues." (PMID 32134969, 2020). "In T2DM, insulin resistance is initially compensated by increased secretion of insulin; however, this prolonged hyperinsulinemia leads to progressive β-cell exhaustion and degradation." (PMID 32425738, 2020).